KRAS (KRas proto-oncogene, GTPase)
Diseases named in the same sentence as KRAS in open-access papers (continued):
Sharing a sentence is not in itself a finding about the gene and the disease.
cancer (continued). "Recent findings indicate that oncogenic KRAS mutations occur in normal tissues and that KRAS activity needs to exceed a threshold to drive cancer progression and metastasis." (PMID 31980649, 2020). "ARS-853, a potent G12C allele-specific inhibitor, reduced KRAS signaling and cancer cell growth in vitro." (PMID 32560574, 2020). "Of the numerous existing RAS proteins, KRAS has a crucial role in proto-oncogene activity, and its mutation status has been highly explored for therapeutic response in cancer research." (PMID 32397507, 2020). "Mutations in KRAS or BRAF genes appear to play an important role in the regulation of metabolic reprogramming in multiple cancers, including CRC." (PMID 32231083, 2020). "The efficacy of such small molecules are demonstrated in human cancer cell cultures, where this compound inhibits the proliferation of cells containing the KRAS G12D allele with some preference." (PMID 32715349, 2020). "In 2019, Amgen and Mirati Therapeutics announced covalent irreversible inhibitors as a treatment for cancer that targeted one form (G12C) of mutated KRAS (AMG 510 and MRTX 849)." (PMID 33297561, 2020). "KRAS mutations are overwhelmingly represented in cancers as whole compared to the other two isoforms." (PMID 31941155, 2020). "We postulate that mucinous KRAS mutated cancers are especially vulnerable to this co‐treatment based on their unique phenotypic and genotypic characteristics." (PMID 31958897, 2020). "The mutant proteins encoded by these germline KRAS mutations are less biochemically and functionally activated than those in cancer." (PMID 32990679, 2020). "This indicates prominant roles for KRas mutations in cancer, which are most frequent in pancreatic (<60%), colon (<30%), and lung (<15%) cancers." (PMID 32456244, 2020). "In this regard, oncogenic KRAS not only drives cancer cell proliferation, but it has been implicated in metastasis formation and in driving the cancer stem-like phenotype." (PMID 32823550, 2020). "Kirsten rat sarcoma viral oncogene homolog (K-Ras) is an upstream regulator of BRAF and the mutant KRAS is associated with aggressive cancer phenotypes and poor patient prognosis." (PMID 33299639, 2020). "For the 14 ctDNA samples of cancer patients, 3 of them generated PCR products when mutation‐specific primers were used, and the presence of point mutations of KRAS in the 3 samples was further confirmed by DNA sequencing." (PMID 32207862, 2020). "KRAS in MMs is infrequently mutated, although it is one of the most frequently mutated proto-oncogenes in human cancers." (PMID 32637031, 2020). "This upregulation requires ERK activity and inhibition of p38 and was also observed in other cancer cells carrying KRAS, BRAF, or NF1 mutations, suggesting that p38 antagonizes this resistance pathway in several different cancer types." (PMID 32046099, 2020). "KRAS mutations lead to the recruitment of Th17 cells and IL-17 production and are associated with tumourigenesis in several cancers." (PMID 33116132, 2020). "In univariable analysis, high serum cholesterol level was associated with KRAS WT in non recto-sigmoid cancers (p = 0.04)." (PMID 32594310, 2020). "KRAS mutations are detected in numerous human cancers, but there are few effective drugs for KRAS‐mutated cancers." (PMID 31709772, 2020). "On the other hand, in the same histotype of cancer, KRAS mutation frequency can be different by anatomy." (PMID 32725342, 2020). "In contrast, for the 176 patients associated with KRAS G12V, there are three cancer types occupy much of the composition (23% of PADD, 22% of LUAD, and 19% of COAD)." (PMID 31925297, 2020). "Mucinous KRAS mutated colon/appendix cancers demonstrate unique genotypic and phenotypic characteristics that allow for the rational application of MEK‐PI3K inhibitor therapy." (PMID 31958897, 2020).
cancer (continued). "Yu et al68 designed a “modified PNA‐PCR method” to screen KRAS mutation in cancer patients, this mutation shows resistance to epidermal growth factor receptor (EGFR) target therapy." (PMID 32838227, 2020). "This dire situation is, in part, caused by the fact that KRAS-mutant cancers including PDAC are commonly only diagnosed at an advanced stage due to the absence of early symptoms." (PMID 32194994, 2020). "Regarding T1+2 cancer, the positivity of the D-marker panel was an independent risk factor for cancer recurrence, and the adjusted HR (95% CI) was 4.37 (1.05 to 18.26) after adjusting for the age, gender, and KRAS mutation." (PMID 32532105, 2020). "Our data suggest that WT MB21D2 overexpression and its Q311E mutation can positively influence the enrichment of KRAS to mediate aggressive cancer behavior." (PMID 32979859, 2020). "KRAS gene mutations are the most frequently described in the majority of cancers, especially in CRC, and up to 40% of all patients have a known KRAS mutant gene." (PMID 33117801, 2020). "The current competing risk nomogram would help physicians to predict cancer specific death of CRC patients who had KRAS testing." (PMID 32547859, 2020). "KRAS mutant cancers are characterized by typical, cancer-type-specific co-occurring mutations and distinct gene expression signatures." (PMID 32725342, 2020). "Immune-modulatory activities of TRAIL–TRAIL-R interaction: an immune checkpoint for KRAS-mutated cancer?" (PMID 32194994, 2020). "In this respect, several mutations of the KRAS isoforms have been found to be frequently occurring in many types of cancer." (PMID 32715349, 2020). "The KRAS mutations are extremely rare in normal individuals, while they are presented in about 30% of cancer patients." (PMID 32207862, 2020). "For instance, KRAS oncogene mutations are common in various cancers and had been found that ATR or GATA2 transcription factor inhibition is synthetically lethal." (PMID 32883316, 2020). "Our data showed that the disruption of the driver gene mutation in the KRAS G12S allele resulted in the inhibition of cancer cell growth in vitro." (PMID 32308773, 2020). "KRas-4B, the most mutated Ras isoform in different cancers, has been under extensive study for more than two decades." (PMID 33266473, 2020). "The Sanger sequencing confirmed the KRAS gene mutations in the three cancer patients: codon 12 mutations (GGT>AGT, GGT>GCT), codon 12 mutations (GGT>AGT, GGT>AGA), and mutation in codon 13 (GGC>GAC)." (PMID 32207862, 2020). "While PNA clamps have been mostly applied to the analysis of KRAS mutations, there are some other cancer targets to which PNAs have been applied as clamps to detect mutations." (PMID 32059456, 2020). "Previous studies have shown that MEK-ERK depletion reduced the expression of EZH2 in cells with KRAS (G12C) mutation, thereby reducing the level of histone methylation and inhibiting the development of cancer." (PMID 32903217, 2020). "For example, Kirsten rat sarcoma viral oncogene homolog (KRAS) showed a highly prevalent mutation approximately with 25% of all human cancers." (PMID 32210733, 2020). "Establishing the Kirsten rat sarcoma (KRAS) mutational status is essential in terms of managing patients with various types of cancer." (PMID 33114622, 2020).
cancer (continued). "We postulate that these highly mucinous KRAS mutated cancers are especially vulnerable to this co‐treatment based on their phenotypic and genotypic characteristics." (PMID 31958897, 2020). "Several studies not only reported mutations but also amplifications of the KRAS locus in different cancer entities." (PMID 32571252, 2020). "When existing separately, activating EGFR mutations are well defined predictive effects of EGFR-TKIs in NSCLC cancer patients, and while coexisting with KRAS mutations and ALK or ROS1 gene rearrangements, the EGFR-TKIs are predicted to be resistant." (PMID 32770988, 2020). "Only recently, selective inhibitors targeting the KRASG12C mutation, which occurs in a small subset of KRAS-mutant cancer patients, were identified and further developed." (PMID 32612138, 2020). "In 3D co-cultures, primary NSCLC derived cells harboring EGFR mutation responded better to erlotinib treatment than KRAS mutant or KRAS/EGFR wild type (WT) cancer cells." (PMID 32434541, 2020). "A multiplex gene sequencing analysis (ACT Genomics, Singapore) found the cancer to contain KRAS and ABL1 mutations." (PMID 33212880, 2020). "As previous report, our data showed that MB sequencing also detected PIK3CA, ERBB2 and KRAS subclonal mutations, which are linked to therapy response in various cancers." (PMID 32099048, 2020). "Amongst the most common mutations across all cancers that also occurred in GBCs were KRAS G12/G13 (5 samples), PIK3CA H1047/E545/E542 (6 samples) and NRAS Q61 (1 sample)." (PMID 32839463, 2020). "KRAS, one of the most frequently mutated oncogenes in cancer, is known to act as a critical driving force in cancers like colorectal and pancreatic cancers." (PMID 32244839, 2020). "KRAS mutation frequencies in human cancer and data from mouse models suggest that a limited quantitative range of RAS signal (a “sweet spot”) is critical for the development of tumors." (PMID 33073539, 2020). "Ras as a most frequently mutated oncogene and associated with particular poor disease prognoses in cancer, the enormous effort had been made to develop drugs that target KRAS mutations directly or indirectly." (PMID 32244355, 2020). "The Ras genes (KRAS, NRAS, HRAS) are the most frequently mutated oncogenes in human cancers, with KRAS showing the highest overall mutation frequencies." (PMID 32581224, 2020). "One of these is siG12D LODER, which is a siRNA against the cancer-associated mutant KRAS (siG12D) encapsulated in a miniature biodegradable implant, Local Drug EluteR (LODER)." (PMID 32373584, 2020). "The G12 mutation of KRAS is one of the main driver mutations in human cancer, which is now thought to be presented on some pMHC alleles in some patients." (PMID 33298945, 2020). "There is an ongoing phase I trial (NCT04111458) evaluating the clinical benefit of SOS1: KRAS inhibition, alone and in combination with trametinib, in advanced KRAS-mutated cancers." (PMID 32967105, 2020). "Another cancer vaccine has been developed against the Ras protein antigen, a product of the KRAS gene, which is mutated in the vast majority of PDAC tumors." (PMID 33050151, 2020). "Due to its frequent mutations in multiple lethal cancers, KRAS is one of the most‐studied anticancer targets nowadays." (PMID 32237114, 2020). "KRAS is mutated in 85% of all RAS-mutated cancers and it plays a key role in the development of many aggressive malignancies, such as pancreatic cancer." (PMID 32887255, 2020). "In this patient, KRAS was the only additional cancer gene besides FOXL2 and TERT that was mutated in all samples." (PMID 32455687, 2020).
cancer (continued). "To investigate the potential role of miR181ab1 in human cancer, we queried its association with oncogenic KRAS expression in vitro." (PMID 31874105, 2020). "In the present study, we aimed to assess the response to EGFR-TKIs of cancer cells with EGFR/KRAS co-mutations." (PMID 32130260, 2020). "KRAS is the most frequently mutated oncogene in cancer, due to its presence in the predominant types like lung (NSCLC), pancreatic and colorectal adenocarcinomas." (PMID 33297561, 2020). "KRAS is the most frequently mutated oncogene in human cancer, particularly in cancers with a high mortality rate such as pancreatic, colorectal, and non-small cell lung cancer (NSCLC)." (PMID 32550498, 2020). "From all of the RAS isoforms, KRAS is the most oncogenic with its 85% share of all mutated RAS proteins observed in cancer." (PMID 31988705, 2020). "One exception is paclitaxel-KRAS, in which the drug sensitivity increased with mutation cancer diversity." (PMID 31925297, 2020). "KRAS mutations are detected in many highly malignant cancers, such as pancreatic ductal adenocarcinoma, colorectal adenocarcinoma, and lung adenocarcinoma." (PMID 33138914, 2020). "This study strongly suggests that ASCT2 is an excellent target molecule for the treatment of malignancies, especially KRAS‐mutated cancers." (PMID 31709772, 2020). "Previously, it has been demonstrated that many human cancer cell lines with KRAS activating mutations have basal levels of autophagy." (PMID 32655498, 2020). "Previous studies have reported that KRAS-mutated cancer cells help to build an immunosuppressive environment by regulating immune cells behavior in PC." (PMID 33316775, 2020). "We therefore estimated the cancer cell content of biopsy samples using Sanger sequencing to detect the likely truncal KRAS/NRAS mutations identified previously by clinical sequencing assays." (PMID 33014822, 2020). "In conclusion, the combination of MEK inhibitor GDC-0623 and agonist anti-CD40 Ab is a highly potent regimen for the treatment of tumors, especially for cancers such as PDA that are driven by mutated KRAS and heavily infiltrated by myeloid cells." (PMID 32358491, 2020). "Results confirmed a significant association between high chol:HDL ratio and KRAS mutation in recto-sigmoid cancers (OR 3, CI 1.3–6.8, p = 0.009)." (PMID 32594310, 2020). "Recent work has shown that activating KRAS mutations can drive an immunosuppressive response in cancer cells through increased PD-L1 expression." (PMID 31940491, 2020). "Studies have shown that KRAS regulated signaling pathways range from ECM changes to endothelial cell signals or the modulation of cancer-associated fibroblasts and inflammatory/immune cells." (PMID 32626534, 2020). "Collectively, these findings indicate that ROS production and redox alterations represents a central mechanism through which the STS and vitamin C combination selectively kills KRAS mutated cancer cells." (PMID 32393788, 2020). "Of note, PI3K pathway are a potential candidate not only in KRAS mutant cancers, but also in solid tumors harboring NRAS mutations." (PMID 32524209, 2020). "Although the importance of glutamine in KRAS‐mutated cancers has been investigated, the exact effects of the KRAS mutation status on ASCT2 function are unclear." (PMID 31709772, 2020). "First, accumulating evidence demonstrates that KRAS, one of the most frequently mutated genes in human cancers, plays a critical role in the maintenance of a cancer stem-like phenotype." (PMID 32823550, 2020).
cancer (continued). "We show that, for the first time, protein-tyrosine phosphatase non-receptor type 2 (PTPN2) regulates the KRAS plasma membrane association and plays an important role in KRAS-dependent cancer cell proliferation and survival." (PMID 33122197, 2020). "PDAC arises from cancer precursor lesions known as Pancreatic Intraepithelial Neoplasia (PanIN) and oncogenic KRAS mutations are an early event in low grade PanIN." (PMID 32756381, 2020). "The Ras-binding domain of the protein kinase c-Raf (c-Raf-RBD) is the tightest known binder of KRas, a protein implicated in difficult-to-treat cancers." (PMID 32511232, 2020). "The Ras/MAPK (Ras/mitogen activated protein kinases) pathway and its continuous activation, due to mutations presented in codon 12 of the KRAS gene, plays an important role in treatment resistance in patients with various carcinomas, including CRC." (PMID 32471257, 2020). "It has been reported that CRAF is a best target for carcinoma with KRAS mutations and intensifies MAPK signaling." (PMID 32556513, 2020). "Mutations in KRAS are present in 22% of all human cancers, and known to be activators of MAPK signaling." (PMID 31277422, 2019). "Here, the authors show that LIF expression is specifically induced by KRAS and constitutes a potential target to treat these KRAS-mutated cancers." (PMID 31296870, 2019). "In fact, the first clinical trial to test this immunotherapy regimen in HLA-A11:01 cancer patients with KRAS G12V mutation has begun (NCT03190941)." (PMID 31781598, 2019). "KRAS is one of the most common mutated oncogenes in cancer, a powerful promoter of tumorigenesis, a strong induction factor for malignant tumors, and a predictive biomarker of therapeutic response." (PMID 31073530, 2019). "In this model, loss of GLI1 impaired KRAS-induced pancreatic carcinogenesis, revealing a targetable KRAS-driven mechanism underlying the crosstalk between cancer cells and the pancreatic stromal compartment." (PMID 31847096, 2019). "Many factors can drive epithelial plasticity, including activating mutations in KRAS, which are found in an estimated 30% of all cancers." (PMID 31681587, 2019). "The great success of immunotherapy has been witnessed in the treatment of patients with various tumors, but more evidence is required in cancer patients with KRAS mutations." (PMID 31612108, 2019). "The oncogene KRAS is reported to be required for the initiation of cancer and is associated with poor prognosis and poor patient survival." (PMID 30927008, 2019). "Synthetic lethality has emerged as a new strategy for treating cancers driven by refractory mutations that are difficult to be targeted, such as KRAS mutations." (PMID 30674639, 2019). "Fourteen NSCLCs revealed intratumor heterogeneity of KRAS point mutation defined as the coexistence of two different mutations in cancer tissue." (PMID 30368666, 2019). "On the other hand, numerous hotspot cancer gene mutations (including KRAS mutation) were recently detected in EBC–DNA obtained from healthy subjects (cigarette smokers and nonsmokers) using the more sensitive amplicon-based next-generation sequencing method." (PMID 30368666, 2019). "It has recently been reported that activated KRAS can trigger cell death via apoptosis and autophagy-associated cell death in cancer cells." (PMID 30971271, 2019). "For this purpose, the KRAS gene was detected, which has been commonly found to contain mutations in cancer cells." (PMID 31817059, 2019). "KRas mutations are present in about 30% of all human cancers and KRas-driven cancers have been largely resistant to therapeutic intervention, and KRas itself has been considered undruggable." (PMID 31489935, 2019).